PON1 (paraoxonase 1)
Diseases named in the same sentence as PON1 in open-access papers (continued):
Sharing a sentence is not in itself a finding about the gene and the disease.
atherosclerosis (continued). "PON1 plays an antioxidant role in lipid metabolism, and these actions of PON1 can exert a protective effect on the progression of atherosclerosis and cardiovascular disease." (PMID 37948561, 2023). "Experimental atherosclerosis in rodents has provided consistent evidence that PON1 infusion or over-expression can suppress atherogenesis or that inhibition or ablation of the PON1 gene promotes atherogenesis." (PMID 36873390, 2023). "This has had two major effects on progress in research into the involvement of PON1 in atherosclerosis." (PMID 36873390, 2023). "It is noteworthy that PON1 contributes to the prevention of secondary complications in diabetes, such as atherosclerosis, by hydrolyzing ox-LDL and fatty acids in the blood." (PMID 37627561, 2023). "Previous work has suggested increased Pon1 protects against atherosclerosis and lipid oxidation in a dose-dependent manner." (PMID 37146172, 2023). "PON1 activities suppress the oxidation of LDL which is the initiator of atherosclerosis in the arterial intima." (PMID 36344946, 2022). "PON1 also diminishes monocyte chemotaxis and adhesion to endothelial cells, thereby preventing endothelium damage and atherosclerosis." (PMID 36741829, 2022). "In recent years, PON1 has been proven to play a protective role in many human diseases, such as oxidative stress, atherosclerosis, neurological disorders, cardiovascular, cancer, diabetes, and aging." (PMID 35746674, 2022). "Although PON1 is a serum protein, it has been shown to accumulate in arterial walls during the development of atherosclerosis as part of a protective mechanism to prevent oxidation and disease progression." (PMID 35327606, 2022). "Impaired PON1 PON and ARE activity has been found in inflammatory diseases associated with accelerated atherosclerosis, such as RA." (PMID 36291691, 2022). "The next step was to study the therapeutic effect of PON1 nitrosylation with respect to oxidation and atherosclerosis." (PMID 35327606, 2022). "The available evidence indicates that PON1 plays an important role in inflammation and cancer and atherosclerosis, whereas its role in type I IFN signaling pathway regulation is not known yet." (PMID 35746674, 2022). "What can be seen clearly is that every factor that influences PON1 serum levels will certainly influence the HDL anti-oxidative potential, thus be associated with atherosclerosis." (PMID 36118876, 2022). "PON1 is considered to be involved in the development of oxidative stress-related diseases, such as osteoporosis, atherosclerosis, coronary heart disease, diabetes, and metabolic syndrome." (PMID 35646794, 2022). "In vitro and model animal studies have provided strong support for the conclusion that PON1 protects against the development of atherosclerosis by protecting HDL and LDL from oxidation and reducing oxidative stress." (PMID 35327606, 2022). "Given the previously postulated, we can deduce that carriers of PON1 polymorphisms known to lead to augmented enzyme levels and activity, may have lower susceptibility to oxidation and inflammation, thus lowering the incidence of accelerated atherosclerosis and CVD, and vice versa." (PMID 36118876, 2022). "PON1 prevents atherosclerosis through its antioxidant activity, anti-inflammatory action, anti-apoptosis, anti-thrombosis, anti-adhesion, and lipid-modifying properties." (PMID 33762698, 2021). "PON1 knock-out mice on a high-fat, high-cholesterol diet develop atherosclerosis more rapidly, and the LDL in their artery walls is more highly oxidised than in controls." (PMID 33917627, 2021).
atherosclerosis (continued). "The effect of PON1 on the vasodilatation was also investigated, because endothelial dysfunction is regarded as the earliest stage of atherosclerosis." (PMID 33670025, 2021). "Conversely, overexpression of PON1 protects mice from atherosclerosis, suggesting that PON1 is strongly antiatherogenic in vivo." (PMID 34634315, 2021). "Deletion of Pon1 in the atherosclerosis-prone Apoe−/− mice (Apoe−/−; Pon1−/− mice) exacerbated atherosclerosis compared with Apoe−/−; Pon1+/+mice." (PMID 34331945, 2021). "Paraoxonase 1 (PON1) is known for preventing atherosclerosis through lipid-modifying features, antioxidant activity, anti-inflammatory, anti-apoptosis, anti-thrombosis, and anti-adhesion properties." (PMID 33762698, 2021). "Reduced activity of paraoxonase 1 (PON1), a high-density lipoprotein (HDL)-associated enzyme, has been implicated in the development of atherosclerosis." (PMID 34331945, 2021). "The studies reported here suggest the need for additional studies to determine the extent to which IsoLG modification of PON1 contributes to reduced PON1 activity in vivo and to progression of atherosclerosis." (PMID 34331945, 2021). "The adenovirus-mediated expressions of human PON-1 remarkably reduce the progress of atherosclerosis, artery plaque volume, oxidized LDL levels, and oxidative stress in the coronary plaques and plasma." (PMID 33936387, 2021). "Findings suggest a role for PON1 against atherosclerosis and obesity and protective capacity against bacterial, parasitic, and viral infectious diseases." (PMID 34566994, 2021). "Impaired PON1 PON and ARE activity has been found in inflammatory diseases associated with accelerated atherosclerosis, such as RA and AS." (PMID 34680168, 2021). "PON1 is an enzyme, which is of special significance in relation to atherosclerosis prevention, as it is attached to HDL (high-density lipoprotein) and protects LDL (low-density lipoprotein) from oxidation." (PMID 34917230, 2021). "Recent studies have found that PON-1 can prevent atherosclerosis through direct and indirect approaches." (PMID 32528406, 2020). "It has been proved that PON1 polymorphism is associated with low-density lipoprotein (LDL) oxidation, which plays an important role in artery atherosclerosis." (PMID 32148648, 2020). "Decreased PON1 enzyme activity has been shown to increase inflammation in animal studies and increase oxidative stress among patients with atherosclerosis, diabetes." (PMID 32280543, 2020). "The current experiments showed that TIC, when administered at a dose that inhibits platelet aggregation to the same degree as CLO, protects against atherosclerosis more robustly than CLO likely through its unique ability to induce PON1." (PMID 31242230, 2019). "PPARγ activates the PON1 gene, increasing synthesis and release of PON1 from the liver and reducing atherosclerosis." (PMID 31252610, 2019). "Emerging evidence supports the role of PON1 and PON3 (HDL associated enzyme) in prevention of atherosclerosis." (PMID 31816846, 2019). "This review aims at summarizing the role of PON1 in whole-body lipid and glucose homeostasis, as well as its importance in metabolic disorders, such as atherosclerosis, Diabetes Mellitus(DM), and NAFLD." (PMID 31430977, 2019). "Further investigation is needed to definitively test the notion that TIC protects against atherosclerosis through PON1 induction." (PMID 31242230, 2019). "Among the 48 concordantly upregulated genes, only PON1 has been shown to ameliorate atherosclerosis." (PMID 31242230, 2019). "The increased activity of hemostatic parameters and lowered activity of PON-1 in patients with CD suggest changes in atherosclerosis." (PMID 30314292, 2018). "PON1 has been reported to be beneficial in preventing atherosclerosis, attributing to its ability to reduce lipid hydroperoxides." (PMID 30322078, 2018).
atherosclerosis (continued). "In the current study we investigated PON1 in familial hypercholesteremia due to its role in diverse physiological and pathophysiological functions, including atherosclerosis and inflammatory diseases." (PMID 30044465, 2018). "Navab et al35 also showed that reduced activity of PON1 causes declined ability of HDL against oxidation of LDL which can trigger the formation of atheroma plaques, atherosclerosis, and CVDs." (PMID 29118945, 2017). "PON1 activity is inversely related to atherosclerosis: it is lower in diseases accelerating development of atherosclerosis and it is reduced in inflammatory diseases." (PMID 28376720, 2017). "The physiological role of PON1 is supposedly hydrolysis of homocysteine lactone, which prevents homocysteinilation of proteins and development of atherosclerosis." (PMID 28718803, 2017). "PON1 retards or reverses atherosclerosis via the prevention of low-density lipoprotein cholesterol (LDL-C) oxidation or metabolism of oxidized LDL-C (ox-LDL); it is therefore considered a major factor in the antioxidative activity of HDL-C." (PMID 28038449, 2017). "PON1, which is associated with HDL-C, hydrolyses the oxidized LDL-C and thereby retards the development of atherosclerosis." (PMID 28038449, 2017). "DM is a condition of oxidative stress and resulted in the reduction of PON1 antioxidant activity and the development of atherosclerosis." (PMID 28038449, 2017). "In the long term, decreased PON1 enzyme activity can result in the development and progression of atherosclerosis and CAD due to increased reactive oxygen species and enhanced LDL oxidation." (PMID 29118461, 2017). "Many studies have focused on the association of PON1 and CAD and have demonstrated PON1 activity was decreased in CAD, MI and atherosclerosis." (PMID 28038449, 2017). "Paraoxonase-1 (PON1) is the antioxidant marker of high-density lipoproteins protecting against atherosclerosis and coronary artery disease (CAD) phenotype." (PMID 29118461, 2017). "PON1 protects LDL and HDL against oxidation, and lower serum PON1 levels were associated with higher susceptibility of LDL oxidation and atherosclerosis risk." (PMID 27876051, 2016). "The positive effect of simvastatin treatment on PON1 activity and reduction in oxidative stress markers could be disguised by other factors which reduce the effectiveness of simvastatin, such as coexisting medical treatment, atherosclerosis burden, or coexisting risk factors for atherosclerosis." (PMID 27213056, 2016). "PON1 enzyme is tightly associated with HDL particles and protects both LDL and HDL from oxidation, a major step in the progression of atherosclerosis, the underlying pathophysiologic factor for the majority of cardiovascular diseases." (PMID 27338244, 2016). "PON1 activity is reduced in many diseases such as atherosclerosis, diabetes mellitus, chronic kidney disease, and hypercholesterolemia." (PMID 27642496, 2016). "PON1 and PON2 were both shown to protect from atherosclerosis development, secondary to HDL-associated PON1 antiatherogenic effects in the circulation and in the arterial wall and to PON2 antiatherogenic effects only in the arterial wall." (PMID 26779262, 2015). "Paraoxonases (PON) 1 and 3, which inhibit lipoprotein oxidation and atherosclerosis, and other antioxidant enzymes were involved in CCl4-induced liver injury in rats." (PMID 26199636, 2015). "One of the major discoveries of our study, after assessment of the severity of atherosclerosis using the Gensini score, was that 8-iso-PGF2α levels were positively, and PON-1 activity was negatively, correlated with the severity of coronary artery disease." (PMID 26697134, 2015). "The physiological role of PON1 in reducing atherosclerosis stems from its ability to inhibit the oxidation of low density lipoprotein (LDL) and its ability to stimulate cholesterol efflux from macrophages." (PMID 24799979, 2014).
atherosclerosis (continued). "Quercetin has also been reported to inhibit the progression of atherosclerosis via up-regulating the expression of PON1; indicating a possible cholesterol reverse transportation mechanism." (PMID 24890098, 2014). "Although influences of PON1 and oxidative stress have been demonstrated to be on the early steps of atherosclerosis, our results exclude measurements of PON1 activity and indices of antioxidant status in prediction of atherosclerotic risk." (PMID 24799979, 2014). "This property enabled investigators to propose that PON1 plays a key role in the protection against atherosclerosis and its related systemic diseases." (PMID 25405733, 2014). "In the atherosclerosis process, PON1 accumulates in the artery wall, and PON1(−/−) mice have been shown to have greater levels of oxidized LDL and larger atheromatous plaques when fed a proatherogenic diet." (PMID 23766557, 2013). "HDL-associated PON1 retards oxidation of LDL and therefore inhibits the progression of atherosclerosis." (PMID 23691522, 2013). "PON1 is directly involved in the pathogenesis of atherosclerosis by the modulation of NO bioavailability." (PMID 24222847, 2013). "PON1 also contributes to the attenuation of atherosclerosis development by leading to the formation of lysophosphatidylcholine, which, in turn, stimulates HDL binding and HDL-mediated macrophage cholesterol efflux via the ABCA1 transporter." (PMID 23691522, 2013). "The clinical interest in human PON1 has been mainly focused on atherosclerosis and cardiovascular disease, since PON1 exerts antioxidant and anti-inflammatory roles." (PMID 22536510, 2012). "There is growing evidence from experimental, clinical and epidemiological studies that underscores the role of PON1 in protection against atherosclerosis; however, the precise mechanisms remain elusive." (PMID 22824324, 2012). "PON1 is believed to be responsible for the antioxidant effects of HDL and its activity is inversely associated with the progression of atherosclerosis and the incidence of coronary artery disease." (PMID 22721254, 2012). "This study clearly established the anti-oxidative and anti-inflammatory potential of PON1 in vivo and also showed its potential role in the prevention of atherosclerosis." (PMID 22824324, 2012). "Several lines of evidence have suggested that PON1 protects against atherosclerosis by its evident ability to guard low-density lipoproteins (LDL) against oxidative stress, reduce macrophage foam cell formation, and prevent atherosclerosis development." (PMID 22824324, 2012). "A previous study has shown that PON1 protects against atherosclerosis, by its ability to reduce macrophage foam cell formation, via reducing oxidative stress and stimulation of cholesterol efflux from macrophages." (PMID 22738670, 2012). "The atheroprotective function of PON1 has been also demonstrated in PON1 knock-out mice, which exhibited an accelerated atherosclerosis in contrast to hPON1 transgenic mice where the lesion size was decreased." (PMID 22536511, 2012). "In our research, we found that rabbits treated by probucol have higher PON1 activity than atherosclerosis group." (PMID 22078494, 2011). "The protective role of HDL-C is believed to be mainly due to enzyme paraoxonase 1 (PON1), a Ca++ dependent esterase, bound to its surface which probably prevents atherosclerosis by preventing LDL-C from peroxidation." (PMID 21629682, 2011). "Serum PON1 activity is lower in subjects prone to development of atherosclerosis such as in hypercholesterolemia disease." (PMID 22078494, 2011). "Compared with the control group, the serum PON1 activity was extremely lower in atherosclerosis group, and serum PON1 activity was significantly increase when treated by probucol." (PMID 22078494, 2011). "Animal studies, including PON1-knockout mouse, demonstrated that PON1 deficiency was shown to increase susceptibility to LDL oxidation and atherosclerosis development." (PMID 20804546, 2010).
atherosclerosis (continued). "Serum paraoxonase (PON1) is a high density lipoprotein (HDL)-associated enzyme involved in organophosphate (OP) degradation and prevention of atherosclerosis." (PMID 19922610, 2009). "PON1’s physiologic activity is thought to be that of a lipolactonase whose activity results in the prevention of atherosclerosis." (PMID 19672401, 2009). "High PON1 levels slowed and even prevented the entry of OP into the brain and reduced atherosclerosis signs." (PMID 22649587, 2009). "Although these properties render PON1 an attractive candidate for the treatment of atherosclerosis, and pesticides or nerve agents toxicity, certain characterizations of human PON1 hamper such uses." (PMID 19922610, 2009). "We have recently shown that adenovirus mediated overexpression of human PON1 in a mouse model of metabolic syndrome significantly inhibits atherosclerosis development by reducing ox-LDL both in plasma and the artery wall." (PMID 18937674, 2008). "It is therefore possible that increased levels of medium HDL may be protective against subclinical atherosclerosis by carrying PON1 and effectively promoting the efflux of cholesterol." (PMID 41160327, 2025). "Modulating PON-1 activity may serve as a promising therapeutic target to reduce the prevalence of atherosclerosis and its clinical complications." (PMID 40722971, 2025). "In addition, we examined changes in the activity or levels of proteins (PON1, MPO) of HDL that have been implicated in SLE-related atherosclerosis." (PMID 38514392, 2025). "This study evaluates the effects of vigorous-intensity bodybuilding exercise (VIBBE) on atherosclerosis biomarkers—including paraoxonase-1 (PON1) and arylesterase (ARE) activities—and lipid profiles in male bodybuilders who do not use anabolic-androgenic steroids." (PMID 39459504, 2024). "Numerous studies highlight the protective effects of HDL and PON1 against atherosclerosis and CVDs." (PMID 38474781, 2024). "Animal models suggest a causal link between PON1 present on HDL and atherosclerosis." (PMID 38887979, 2024). "The potential assaying of PON-1 may be more effective than conventional serum HDL levels in predicting atherosclerosis in patients with type II diabetes mellitus." (PMID 39336967, 2024). "Many constituents of HDL are responsible for its role in preventing atherosclerosis, but PON-1 is among the most important of the lipid-modifying features, accounting for its antioxidant activity, anti-inflammatory, anti-thrombotic, and anti-adhesion properties." (PMID 39765763, 2024). "In mice, Pon1 protects from atherosclerosis induced by a high-fat diet or ApoE depletion." (PMID 39125665, 2024). "Paraoxonase 1 (PON 1) is an antioxidantenzyme associated with high-density lipoprotein(HDL), and multiple studies have established a connectionbetween reduced PON 1 activity andincreased atherosclerosis risk." (PMID 39139165, 2024). "Some research has shown that in carriers of the RR genotype, PON-1 enzyme activity decreases, increasing oxidative stress and inflammation; furthermore, all of these events may be related to the occurrence of atherosclerosis and CAD." (PMID 39336967, 2024). "PON1 may exert its antioxidant effect via hydrolyzing and detoxifying oxidized lipids found in oxLDL, a major contributor to atherosclerosis development." (PMID 38474781, 2024). "PON-1 is atheroprotective due to its antioxidant and anti-inflammatory roles in the body; indeed, it prevents LDL oxidation, thereby reducing the risk of atherosclerosis." (PMID 39336967, 2024). "In diabetic patients, PON1 activity is lower, and it can go even lower in those who are also suffering from microvascular complications of diabetes, leading further to a higher chance of developing atherosclerosis." (PMID 38474211, 2024). "Overexpression of PON1 in mouse, rat and rabbit models protects against atherosclerosis." (PMID 38887979, 2024).